SPTBN4 (spectrin beta, non-erythrocytic 4)
Synonyms: KIAA1642; SPTBN3; CMND; NEDHND; QV; SPNB4
Tractability: Antibody: its Gene Ontology location is reachable by antibodies, with medium confidence. PROTAC: ubiquitination databases record sites on it; its protein half-life has been measured.
Gene: Protein-coding gene on chromosome 19 (40,466,241 to 40,576,464, forward strand). Ensembl gene ENSG00000160460.
Subcellular location: Cytoplasm, cytoskeleton; Cytoplasm, cell cortex
Subcellular location (Human Protein Atlas): Nucleoli; Nucleoplasm
Pathways (Reactome):
Developmental Biology: Interaction between L1 and Ankyrins; NCAM signaling for neurite out-growth
Signal Transduction: RAF/MAP kinase cascade
Vesicle-mediated transport: COPI-mediated anterograde transport
Gene Ontology:
Molecular function: ankyrin binding; phosphatase binding; protein binding; actin binding; actin filament binding; cytoskeletal protein-membrane anchor activity; spectrin binding; structural constituent of cytoskeleton; cytoskeletal protein binding; phospholipid binding
Biological process: actin cytoskeleton organization; axonogenesis; cardiac conduction; central nervous system projection neuron axonogenesis; clustering of voltage-gated sodium channels; negative regulation of heart rate; protein localization to plasma membrane; regulation of sodium ion transport; sensory perception of sound; transmission of nerve impulse; vesicle-mediated transport
Cellular component: cytoplasm; extracellular exosome; membrane; nuclear matrix; PML body; spectrin; actin filament; adherens junction; axon hillock; axon initial segment; cell body fiber; cell junction; cortical actin cytoskeleton; cytosol; neuronal cell body; node of Ranvier; plasma membrane; axon; cell cortex; cytoskeleton; intercalated disc; juxtaparanode region of axon; paranode region of axon
Genetic constraint (gnomAD): Loss-of-function variants: 96 observed, 214.92 expected, observed/expected ratio (o/e) 0.45, 90% interval 0.38 to 0.53. The upper end of that interval is the gene's LOEUF score, 0.53, which puts it in group 2 of 6, group 1 being the genes least tolerant of losing a copy. Missense variants: 2,985 observed, 3,083.8 expected, observed/expected ratio (o/e) 0.97, 90% interval 0.94 to 1. Synonymous variants: 1,478 observed, 1,330.6 expected, observed/expected ratio (o/e) 1.11, 90% interval 1.06 to 1.16.
Gene-disease validity (ClinGen):
ClinGen rates the evidence that SPTBN4 causes each of these diseases.
neurodevelopmental disorder with hypotonia, neuropathy, and deafness (autosomal recessive): Definitive.
Homologues: Orthologues: chimpanzee SPTBN4 (99% identical), pig SPTBN4 (97% identical), rat Sptbn4 (96% identical), mouse Sptbn4 (96% identical), guinea pig SPTBN4 (94% identical), rabbit SPTBN4 (65% identical), tropical clawed frog sptbn4 (63% identical), zebrafish sptbn4b (30% identical), macaque SPTBN4 (26% identical). Paralogues in human: SPTBN1 (47% identical), SPTBN2 (44% identical), SPTB (43% identical), SPTBN5 (23% identical), MACF1 (20% identical), DST (20% identical), SYNE1 (20% identical), SYNE2 (20% identical), PLEC (18% identical), DMD (16% identical), UTRN (15% identical), SPTAN1 (15% identical), and 24 more.
Diseases named in the same sentence as SPTBN4 in open-access papers:
SPTBN4 is named in the same sentence as 34 diseases in open-access papers, as found by Europe PMC text mining. Sharing a sentence is not in itself a finding about the gene and the disease. The quoted sentences say what the papers report.
deafness (5 papers, 2018 to 2025). An inherited or acquired condition characterized by the complete loss of the ability to hear from one or both ears. "A variant in a gene that encodes another CAPN5 substrate candidate, SPTBN4, was reported to cause neurodevelopmental disorder with hypotonia, neuropathy and deafness." (PMID 40650235, 2025). "Pathogenic variants in SPTBN4 have been linked to autosomal recessive “neurodevelopmental disorder with hypotonia, neuropathy, and deafness” (MIM# 617519) known as NEDHND." (PMID 40781329, 2025). "We present natural history of SPTBN4-associated neurodevelopmental disorder with hypotonia, neuropathy, and deafness in addition to four Saudi families with ten affected individuals who share clinical features of NEDHND." (PMID 40781329, 2025). "Mice carrying recessive loss‐of‐function Sptbn4 mutations manifest ataxia, motor neuropathy, deafness and tremor." (PMID 29770609, 2018). "Neurodevelopmental disorder with hypotonia, neuropathy, and deafness (NEDHND, OMIM #617519) is an autosomal recessive disease caused by homozygous or compound heterozygous variants in SPTBN4 coding for type 4 βIV-spectrin, a non-erythrocytic member of the β-spectrin family." (PMID 33772159, 2021).
neuropathy (5 papers, 2021 to 2025). A disorder affecting the nervous system that manifests with pain, tingling, numbness, and/or muscle weakness. "Humans and mice with pathogenic Sptbn4 variants have impaired motor function, neuropathy, as well as auditory deficits." (PMID 35393465, 2022). "Mutations in the SPTBN4 gene, which encodes β4-spectrin, are connected to myopathy, neuropathy and auditory deficits in humans." (PMID 36362407, 2022). "Sptbn4 mutations are associated with myopathy, neuropathy, and auditory deficits in humans." (PMID 35393465, 2022).
Intellectual disability (3 papers, 2019 to 2025). "The phenotypic spectrum of SPTBN4 mutations ranges from motor dysfunction to severe intellectual disability." (PMID 40781329, 2025). "SPTBN4 (gene encoding βIV spectrin) has also been associated with intellectual disability, congenital hypotonia, and motor axonal neuropathy." (PMID 31866821, 2019). "We have identified multiple novel variants that affect function of SPTBN4 in patients with severe muscular hypotonia, dysphagia, absent speech, delayed gross motor development, and intellectual disability." (PMID 33772159, 2021).
Ataxia (2 papers, 2018 to 2025). Ataxia refers to impaired coordination of voluntary muscle movement. "Although no NEDHND patients have ever reported having ataxia, SPTBN4 mutant mice demonstrated ataxia." (PMID 40781329, 2025).
congenital myopathies (2 papers, 2021 to 2024). "A frameshift mutation in SPTBN4 can cause congenital myopathy in humans, characterized by a lack of type I muscle fibers." (PMID 39457925, 2024).
Hearing impairment (2 papers, 2009 to 2024). A decreased magnitude of the sensory perception of sound. "First, we identified mostly reduced expression of genes previously associated with loss of function mutations linked to overt hearing loss, including Gfi1, Otog, Mafb, Sema3e, Smpx and Sptbn4, suggesting hidden and overt hearing loss share similar genetic mechanisms." (PMID 39049179, 2024).
Alzheimer disease (1 paper, 2025). A progressive, neurodegenerative disease characterized by loss of function and death of nerve cells in several areas of the brain leading to loss of cognitive function such as memory and language. "Therefore, we speculated that there is a downregulation of SPTBN4 in Alzheimer’s disease, which is indeed supported by previous reports and its epigenetic silencing in patients with Alzheimer’s disease." (PMID 39972214, 2025).
autism (1 paper, 2025). Persistent deficits in social interaction and communication and interaction as well as a markedly restricted repertoire of activity and interest as well as repetitive patterns of behavior. "Variants in SPTBN4 noncoding regions and tandem repeats (TRs) were detected in ADHD and autism patients." (PMID 40781329, 2025). "The most recent reported patients with SPTBN4 variants suffer from attention-deficit hyperactivity disorder (ADHD), autism, and congenital heart defects (CHDs) with no other clinical data available." (PMID 40781329, 2025).
autoimmune thyroid disease (1 paper, 2025). Inflammatory disease of the thyroid gland due to autoimmune responses leading to lymphocytic infiltration of the gland. "KEGG pathway analysis identified significant enrichment of pathways such as cell adhesion molecules, Toll-like receptor signaling, antigen processing and presentation, and autoimmune thyroid disease in the high SPTBN4 expression group." (PMID 40321316, 2025).
cardiomyopathy (1 paper, 2025). A disease of the heart muscle or myocardium proper. "Abnormal expression of SPTBN4 mRNA disturbs Na+ current contributing along with other factors to cardiomyopathy." (PMID 40781329, 2025).
depression (1 paper, 2022). "Another probe in the CpG island located on Chr19:41,035,100-41,035,440, near SPTBN4, showed a borderline statistically significant association with depression (cg02795700, beta = −22.7, log2FC = −0.616, p = 0.053)." (PMID 36421693, 2022).
developmental and epileptic encephalopathy (1 paper, 2022). An epilepsy associated with developmental impairment that may be due to either the underlying etiology or the superimposed epileptic activity, or both. "Mendelian disease-gene links are increasingly being recognized for the spectrin genes, with SPTAN1, SPTBN1, SPTBN2 and SPTBN4 linked to neurological diseases such as developmental and epileptic encephalopathy (DEE), ataxia, hereditary spastic paraplegia, and hereditary motor neuropathy." (PMID 36238261, 2022).
diabetes (1 paper, 2021). "And SPTBN4, a spectrin that links cytoskeletal actin to the plasma membrane, does not yet have a known role in diabetes." (PMID 33795639, 2021).
lung carcinoma (1 paper, 2025). "For instance, overexpression of SPTBN4 is associated with enhanced invasive potential, poor prognosis, and cisplatin resistance in lung cancer." (PMID 40321316, 2025).
lymph node metastatic tumor (1 paper, 2025). "Further IHC analysis confirmed that SPTBN4 presented elevated expression in lymph node metastatic tumor compared to adjacent and primary tumors." (PMID 40321316, 2025).
MODY (1 paper, 2023). "Similarly, in the case of MODY diabetes, the heterozygous MLKL loss-of-function mutation also segregated with heterozygous deleterious mutations in the known MODY gene PDX1, as well as ERN2, NIPAL4 and SPTBN4 in affected individuals." (PMID 36755069, 2023).
Paralysis (1 paper, 2019). Paralysis of voluntary muscles means loss of contraction due to interruption of one or more motor pathways from the brain to the muscle fibers. "The discrepancy between front and hind legs muscle fibers has also been described in quivering mice, in which SPTBN4 loss-off-function mutations cause motor neuropathy, hind limb paralysis, tremors, and central deafness." (PMID 31850074, 2019).
seminoma (1 paper, 2025). A radiosensitive malignant germ cell tumor found in the testis (especially undescended), and extragonadal sites (anterior mediastinum and pineal gland). "Clinically, these findings suggest that SPTBN4 can serve as a diagnostic biomarker to differentiate seminomas from other testicular cancer subtypes." (PMID 40321316, 2025). "Overall, high SPTBN4 expression in seminoma was associated with a broader range of effective chemotherapeutic options, positioning these patients as favorable candidates for chemotherapy." (PMID 40321316, 2025). "Results: scRNA-seq analysis revealed heterogeneous epithelial populations, with Epi1 cells exhibiting SLC5A5 and SPTBN4 as risk factors for advanced progression of seminomas." (PMID 40321316, 2025). "The study establishes SPTBN4 as a potential diagnostic biomarker for distinguishing seminoma subtypes, as well as a prognostic factor, offering a novel target for future therapeutic development." (PMID 40321316, 2025). "Among these, SLC5A5 and SPTBN4 emerged as risk factors for seminoma, whereas PLD4 was identified as a protective factor." (PMID 40321316, 2025). "While SPTBN4 did not demonstrate prognostic significance in normal testicular tissues (p = 0.496, HR = 0.78, 95% CI: 0.39–1.578), subgroup analysis revealed that high SPTBN4 expression was associated with poorer prognosis in seminoma patients (p = 0.032, HR = 9.86, 95% CI: 1.217–79.87)." (PMID 40321316, 2025). "In conclusion, this study establishes SPTBN4 as a key molecular marker for seminomas, bridging gaps in diagnosis, prognosis, and therapeutic response prediction." (PMID 40321316, 2025). "The integration of single-cell transcriptomics, hdWGCNA, and drug sensitivity analyses underscores the molecular complexity of seminomas and highlights the translational potential of SPTBN4 in guiding personalized treatment strategies." (PMID 40321316, 2025). "The functional role of SPTBN4 in seminoma progression likely involves modulating immune evasion mechanisms and shaping an immunosuppressive microenvironment." (PMID 40321316, 2025). "To explore the functional implications of SPTBN4 expression in seminoma, we conducted pathway enrichment analyses comparing groups with high and low SPTBN4 expression levels." (PMID 40321316, 2025). "This study identified SPTBN4 as a pivotal molecular marker for seminomas, highlighting its dual role in precise diagnosis and prognostic prediction." (PMID 40321316, 2025). "Using the GDSC database, we evaluated drug sensitivity in seminoma patients stratified by SPTBN4 expression." (PMID 40321316, 2025). "To elucidate the relationship between SPTBN4 expression, the immune microenvironment, and immunotherapy efficacy in seminoma, we utilized the CIBERSORT deconvolution algorithm to analyze immune cell infiltration." (PMID 40321316, 2025). "This highlights SPTBN4 as a pivotal biomarker for guiding personalized treatment strategies in seminoma." (PMID 40321316, 2025). "Our findings highlight SPTBN4 as a promising biomarker for seminoma diagnosis and prognosis." (PMID 40321316, 2025). "SPTBN4 was markedly upregulated in seminoma compared to nonseminomatous tumors and normal tissues, and its high expression was associated with poorer clinical outcomes and immunosuppressive microenvironments." (PMID 40321316, 2025). "SPTBN4 was identified as uniquely expressed in testicular tumor tissues, with significantly higher levels in seminoma compared to nonseminomatous and mixed tumors (p = 0.0013)." (PMID 40321316, 2025).
testicular seminoma (1 paper, 2025). A malignant germ cell tumor arising from the testis. "The primary discovery of this study is the identification of SPTBN4 as a critical molecular marker for testicular seminomas." (PMID 40321316, 2025). "Besides, the identification of SPTBN4 as a key molecular marker in testicular seminomas is a significant contribution." (PMID 40321316, 2025). "In addition, for the first time, this study links SPTBN4 overexpression with poor prognosis and immune-suppressive microenvironments, offering valuable insights into the immune landscape of testicular seminomas." (PMID 40321316, 2025).
testicular tumor (1 paper, 2025). "In addition to SPTBN4, 31 other molecules were analyzed, revealing potential testicular tumor markers such as TPI1, HMGN1, UGCG, NCL, SET, and EIF3K." (PMID 40321316, 2025).
myopathy (5 papers, 2019 to 2025). A disease of the muscle in which the muscle fibers do not function properly. "Spontaneous or targeted mutations in Sptbn4, a gene encoding β4-spectrin, cause severe neurological dysfunction that includes motor dysfunction, myopathy, and auditory neuropathy in humans." (PMID 35393465, 2022). "The observed phenotype of the affected piglets (myopathy, hind limb paralysis, tremors) was completely congruent with what was observed in human patients with homozygous loss-of-function or compound heterozygous mutations in the SPTBN4 gene (OMIM: 606214)." (PMID 31850074, 2019). "A deletion in the spectrin beta non-erythrocytic 4 protein (SPTBN4) gene affects localization of ion channels in myelinated nerves and causes severe myopathy and postnatal mortality." (PMID 41465565, 2025). "In other words, contrary to prior assumptions, β4 spectrin is likely not required for skeletal muscle health or function; myopathy previously associated with SPTBN4 mutations is possibly neurogenic rather than myogenic." (PMID 40781329, 2025). "We derived that the evidence for a myopathy is mostly from the clinical and histopatholocigal findings, but not from functional studies about the role of SPTBN4 in muscle cells." (PMID 33772159, 2021).
tumor (3 papers, 2023 to 2025). "Conversely, downregulation of SPTBN4 could influence tumor progression and vasculature, suggesting its potential as a diagnostic and a key regulator of tumor angiogenesis in cancer." (PMID 40321316, 2025). "SPTBN4 can influence tumor cell migration, immune evasion, and neovascularization within this context by mediating VEGFR2 internalization and degradation." (PMID 40321316, 2025). "Immune-related processes, such as adhesion and cellular communication, also exhibited notable differences, suggesting a pivotal role for SPTBN4 in tumor–immune microenvironment interactions." (PMID 40321316, 2025). "These pathways are known to influence tumor immune suppression and progression, further substantiating the potential role of SPTBN4 in immune modulation." (PMID 40321316, 2025). "As such, SPTBN4's involvement in the TME provides new avenues for research in tumor diagnosis and therapy, highlighting its potential as a therapeutic target." (PMID 40321316, 2025). "By contrast, tumors with low SPTBN4 expression display a more active immune profile and signaling pathways conducive to tumor suppression." (PMID 40321316, 2025). "For example, SPTBN4 modulates the interaction between tumor cells and the extracellular matrix, potentially facilitating matrix degradation and enhancing tumor invasiveness." (PMID 40321316, 2025). "The shared regions within fresh tissue tumor and fresh PDC involve intergenic variants (location 20:26485669–26599574), and SPTBN4 and the intergenic variant (location 4:126332603–126332715) are common in fresh PDC and cryopreserved PDC." (PMID 38744935, 2024). "By affecting cell adhesion, motility, and cell cycle regulation, SPTBN4 may promote tumor cell growth and metastasis." (PMID 40321316, 2025).
neurologic disorders (2 papers, 2022 to 2023). "The first 3 β-spectrin genes (SPTBN1, SPTBN2, and SPTBN4) are responsible of multiple neurologic disorders, depending on the gene and inheritance pattern." (PMID 36331550, 2023). "Variants in the spectrin genes SPTAN1, SPTBN1, SPTBN2, and SPTBN4 have been associated with neurological disorders; however, SPTBN5 gene-variants have not been associated with any human disorder." (PMID 35782384, 2022). "In addition, mutations in various members of the spectrin gene family are associated with erythroid cell disorders (SPTA1, SPTB) and neurological disorders (SPTAN1, SPTBN1, SPTBN2, and SPTBN4); however, no human genotype-phenotype correlation has been established for SPTBN5 to date." (PMID 35782384, 2022).
cancer (1 paper, 2025). A tumor composed of atypical neoplastic, often pleomorphic cells that invade other tissues. "High SPTBN4 expression was significantly associated with increased NET formation, a process implicated in immune suppression and poor outcomes in cancer immunotherapy." (PMID 40321316, 2025).
SPTBN4 also shares sentences with these, for which no sentence is quoted: neurodevelopmental disorder (2 papers); neurodevelopmental disorder with hypotonia, neuropathy, and deafness (2); axonal neuropathy (1); Cerebral atrophy (1); developmental delay (1); melanoma (1); Motor axonal neuropathy (1); Neurodevelopmental delay (1); testicular cancer (1); Tremor (1).